BMERB1 (bMERB domain containing 1)
Synonyms: C16orf45; FLJ32618; MINP
Tractability: PROTAC: ubiquitination databases record sites on it.
Gene: Protein-coding gene on chromosome 16 (15,434,475 to 15,625,028, forward strand). Ensembl gene ENSG00000166780.
Subcellular location (Human Protein Atlas): Cytosol; Nucleoplasm
Gene Ontology:
Molecular function: protein binding
Biological process: negative regulation of microtubule depolymerization
Cellular component: microtubule cytoskeleton
Genetic constraint (gnomAD): Loss-of-function variants: 11 observed, 21.24 expected, observed/expected ratio (o/e) 0.52, 90% interval 0.32 to 0.86. The upper end of that interval is the gene's LOEUF score, 0.86, which puts it in group 3 of 6, group 1 being the genes least tolerant of losing a copy. Missense variants: 241 observed, 258.24 expected, observed/expected ratio (o/e) 0.93, 90% interval 0.84 to 1.04. Synonymous variants: 117 observed, 99.38 expected, observed/expected ratio (o/e) 1.18, 90% interval 1.01 to 1.37.
Homologues: Orthologues: chimpanzee BMERB1 (99% identical), guinea pig BMERB1 (99% identical), macaque BMERB1 (99% identical), dog BMERB1 (97% identical), pig BMERB1 (97% identical), rat Bmerb1 (96% identical), mouse Bmerb1 (95% identical), tropical clawed frog bmerb1 (73% identical), zebrafish bmerb1 (55% identical).
Diseases named in the same sentence as BMERB1 in open-access papers:
BMERB1 is named in the same sentence as 14 diseases in open-access papers, as found by Europe PMC text mining. Sharing a sentence is not in itself a finding about the gene and the disease. The quoted sentences say what the papers report.
breast tumor (1 paper, 2024). "The capability of STGIC is validated indirectly by expression of marker genes of invasive breast tumor in the predicted spatial domains, which are C6orf141, PDE5A, LINC00645, BMERB1, ABCC11, ABCC12." (PMID 38416785, 2024).
prion disease (1 paper, 2025). A transmissible disease that is caused by a protein that is able to induce abnormal folding of normal cellular proteins, leading to characteristic spongiform brain changes, which are associated with neuronal loss without an inflammatory response. "Several other subthreshold hits were also identified with potential relevance to prion disease mechanisms, including the previously identified subthreshold GWAS hit, BMERB1." (PMID 39865733, 2025).
BMERB1 also shares sentences with these, for which no sentence is quoted: asthma (1 paper); brain disease (1); breast carcinoma (1); cancer (1); Hyperglycemia (1); Infertility (1); Insulin resistance (1); meningioma (1); migraine (1); neurodevelopmental disorder (1); schizophrenia (1); thyroid carcinoma (1).